IL1B (interleukin 1 beta)
Diseases named in the same sentence as IL1B in open-access papers (continued):
Sharing a sentence is not in itself a finding about the gene and the disease.
lymphoma (continued). "To observe the risk of thrombosis in hematologic malignancies, we examined the levels of inflammatory factors IL-1β, TNF-α, TGF-β, and MCP-1 as well as coagulation factors FVIII, TF, P-selectin, thrombin, and fibrinogen in the plasma of patients with lymphoma." (PMID 40076681, 2025). "In response to tissue injury, IL-1β and coagulation FVIII are increased, but we demonstrated their lower levels that question the relevance of tissue injury in thrombosis of lymphomas." (PMID 40076681, 2025). "Previous study showed high levels of IL-10, IL-6, IL-1β, and TNF-α in lymphoma patients except TNF-α in NHL patients." (PMID 40076681, 2025). "Apart from its effect on BCR signaling and its ability to induce apoptosis in lymphoma cells, Luxeptinib was also shown to inhibit NLRP3-mediated IL-1β secretion in monocytic cell lines." (PMID 38397043, 2024). "Essentially, mRNA levels of NLRP3, IL-1β, IL-18, caspase-1, and P2 × 7R, components of the NLRP3 inflammasome, were significantly elevated in SjS patients who subsequently developed lymphoma." (PMID 35897704, 2022). "As AP‐1 subunit c‐Jun was shown to up‐regulate LGALS1 expression through AP‐1 site in lymphoma cells, we examined the involvement of AP‐1, mainly composed of ATF, Fos and Jun family protein dimers, in IL‐1β‐stimulated LGALS1 expression in Müller glial cells." (PMID 31328390, 2019). "Our result showed high levels of IL-10, IL-6, IL-1β, and TNF-α in lymphoma patients compared with control." (PMID 30814315, 2019). "Expression of B cell-stimulatory cytokines IL-1β, IL-6, IL-10, IL-12p40, IL-13 and TNFα and HIV proteins p17, gp120 and nef were elevated in the Tg mice with lymphoma." (PMID 23985023, 2013). "Evidence that IL‐1β may have anti‐tumor activity was first presented 30 years ago, when intraperitoneal injection of recombinant human IL‐1β induced T‐cell‐dependent regression of subcutaneous SA1 sarcoma and L5178Y lymphomas in mice." (PMID 32770571, 2020). "This study showed that different inflammatory factors such as lipopolysaccharide, 12-o-tetradecanoylphorbol-13-acetate, hydrogen peroxide, okadaic acid, and ceramide induced the production of IL-1b and TNF-α in human pulmonary epithelial cells (A-549), fibroblast (HFL1), and lymphoma cells." (PMID 31827685, 2019). "Our study found that the expression levels of NLRP3-related genes IL-18, IL-1β, NLRP3 and caspase-1, were increased after addition of ATP plus LPS, suggesting NLRP3 could be primed and activated in lymphoma cells." (PMID 29312552, 2017). "The activation of NLRP3 may increase the expression of NLRP3-related genes such as IL-18, IL-1β, NLRP3 and caspase-1 in lymphoma cells, thereby promoting proliferation, inhibiting apoptosis, and reducing the anti-tumor effect of dexamethasone." (PMID 29312552, 2017). "DOX combined with SM can enhance the anti-tumor effect, and induce apoptosis of lymphoma cells and inhibit the expression of inflammatory factors related to tumorigenesis depending on the regulation of Bcl-2 family-mediated mitochondrial pathways, such as TNF-α and IL-1β." (PMID 34120620, 2021). "Also, we found an evidence for the diagnostic utility of the following markers: MCP-1, eotaxin, IL-10 and IL-6 for NHL and HL and IL-1β for HL, while TNF-α has limited utility due to the poor ability to discriminate amongst patients with lymphoma and healthy control, as well as IL-1β for NHL." (PMID 30814315, 2019). "In addition, we observed co-expression of immune mediators, such as interferons and their targets (IFNA1-2, IFNA7-8, IFNB1, and IFNG), as well as proinflammatory cytokines (IL-1B and IL12B) and chemokines and their receptors (CXCL9-11 and CXCR3) by CpG(B)-STAT3dODN-treated lymphoma cells (right)." (PMID 29433938, 2018). "The researchers reported significantly higher mRNA expression for P2X7R, NLRP3, caspase-1, IL-18, and IL-1β in patients with SS who developed MALT-NHL over the follow-up, compared to both SS patients who did not develop lymphoma and controls." (PMID 38397043, 2024).
Thrombocytopenia (29 papers, 2008 to 2026). A reduction in the number of circulating thrombocytes. "Another important proinflammatory cytokine, IL-1β, was also shown to be increased in pSS-associated thrombocytopenia compared to general pSS in our study." (PMID 33767707, 2021). "Another key finding from our analysis is the increased level of IL-8 and IL-1β expression in pSS-associated thrombocytopenia." (PMID 33767707, 2021). "Just as an example, the -31 T > C SNP of the il-1β gene was up-regulated in solid tumors associated with thrombocytopenia." (PMID 31991775, 2020). "It is unclear how IL-1β can induce thrombocytopenia in solid tumors, but it is known that -31 T > C SNP can increase susceptibility to thrombocytopenia in these malignancies." (PMID 31991775, 2020). "Except for IL-1β and bNGF, the correlation for all other proteins was negative, suggesting an involvement of these proteins in the pathogenesis of P. vivax associated with severe thrombocytopenia (PvST)." (PMID 33791239, 2021). "However, both IL-1β and IL-8 may also reveal disease activity of pSS-associated thrombocytopenia, but this still requires further study." (PMID 33767707, 2021). "The treatment also significantly reduced disease severity factors such as vascular leakage, thrombocytopenia; mRNA transcript levels of proinflammatory cytokines such as IL-1β and TNF-α; and restored liver function." (PMID 40189910, 2025). "This programmed cell death induced thrombocytopenia and inflammatory cytokine release such as IL‐1β and IL‐18, promoting platelet aggregation, vaso‐occlusion, endothelial permeability and cascaded inflammatory response." (PMID 36852778, 2023). "Synchronous changes were also observed in HMGB1-induced upregulated expression of IL-1β, and thrombocytopenia at 9 h after HS." (PMID 35945940, 2022). "IL-18 shares similar characteristics with IL-1β and is increased in septic patients, particularly in those with thrombocytopenia." (PMID 36439175, 2022). "These association indicate that IL-1β and TNF-α probably induces liver tissue injury, vascular damage and thrombocytopenia." (PMID 33436908, 2021). "As expected, patients treated with IL-1β inhibitory antibody had a higher rate of fatal infections as well as of neutropenia or thrombocytopenia." (PMID 31652822, 2019). "A subset of cytokines consisting of IL-1β, IL-8, IL-6, TNF-α, and IL-10 was also coordinately high and significantly associated with severity of thrombocytopenia in HA patients." (PMID 28628633, 2017). "As for thrombocytopenia, studies revealed that IL-1β together with IL-6 and IL-8, could increase hypercoagulability of whole blood and induce platelet hyper-activation and spreading." (PMID 33767707, 2021). "In patients with pSS-associated thrombocytopenia, no previous studies have reported the role of IL-1β or IL-8." (PMID 33767707, 2021). "The linear regression showed that the levels of IL-1β, IL-2 and IL-12 were associated with altered PDW in Pv-MAL patients, and they may be predictors of the medullar response to thrombocytopenia caused by vivax malaria." (PMID 32696915, 2020). "IL-1β, IL-8, TNF-α and MCP-1 were associated with marked thrombocytopenia." (PMID 18578883, 2008). "With the activation of caspase‐1 and the release of inflammatory cytokines such as IL‐1β and IL‐18, one of the hypotheses of thrombocytopenia is that pyroptosis is one of the cell death pathways of platelets, which may be an important intervention and therapeutic target of inflammation." (PMID 36852778, 2023). "Severe thrombocytopenia was positively correlated with IL-4, CXCL10, IL-6, IL-10 and IFN-γ levels, renal dysfunction was related to an increase in IL-2, IL-1β, IL-17A and IL-8, and hepatic impairment with CXCL10, MCP-1, IL-6 and IFN-γ." (PMID 36178979, 2022).
Thrombocytopenia (continued). "A retrospective analysis of clinical data from 290 SFTS patients from the First and Second Affiliated Hospitals of Anhui Medical University confirmed previously reported abnormalities including lymphocytopenia, thrombocytopenia, elevated levels of AST, ALT, LDH, and cytokines (IL‐6, IL‐1β, TNF‐α)." (PMID 41090515, 2026). "Additionally, EIII-SNPs induce exacerbated thrombocytopenia, worsen hemorrhage pathogenesis, and the induction of pro-inflammatory cytokines TNF-α, IL-1β, IL-6, and anti-inflammatory cytokine IL-10 in mice." (PMID 37298220, 2023). "Notably, levels of secreted IL-1β, expression of CD62P, and thrombocytopenia at 9 h after HS onset were significantly alleviated after pretreatment with EP and anti-HMGB1 antibody." (PMID 35945940, 2022). "The PSS-associated thrombocytopenia group had significantly elevated levels of IL-8 (196.5 ± 73.4 vs. 137.2 ± 52.9, p = 0.033) and IL-1β (158.5 ± 23.6 vs.130.8 ± 38.7, p = 0.047) compared to the pSS without thrombocytopenia group." (PMID 33767707, 2021).
amyotrophic lateral sclerosis (28 papers, 2012 to 2025). Amyotrophic lateral sclerosis (ALS) is a neurodegenerative disease characterized by progressive muscular paralysis reflecting degeneration of motor neurons in the primary motor cortex, corticospinal tracts, brainstem and spinal cord. "C9orf72-SMCR8 complex subunit (C9orf72) hexanucleotide expansion is the most common genetic cause of familial amyotrophic lateral sclerosis (ALS), and IL-1β levels are increased in the cerebrospinal fluid of ALS patients." (PMID 37085930, 2023). "Treatment with violacein significantly decreased pro-inflammatory cytokines such as TNF-α, IL-1β, and IL-6 in the spinal cord of rats with amyotrophic lateral sclerosis (ALS)." (PMID 40430892, 2025). "IL-1β deletion altered the expression of genes involved in extracellular region, including upregulation of PFN1 gene related to amyotrophic lateral sclerosis and increased the expression of the opposite strand of IL-1β." (PMID 37971544, 2024). "Similarly, other research teams have reported increases in the expression and activity of NLRP3, IL-1β, IL-18 and caspase-1 in plaques of MS patients and the tissues of amyotrophic lateral sclerosis (ALS) (or motor neurone disease) patients." (PMID 29052145, 2018). "With respect to amyotrophic lateral sclerosis (ALS), significantly higher blood levels of IL‐1β, IL‐6, IL‐8, TNF‐α, TNF receptor 1 (TNFR1), and vascular endothelial growth factor (VEGF) were found in the disease condition compared to the control group." (PMID 40709483, 2025). "Minocycline inhibits the expression of CD68, cell surface markers of M1 polarized microglia, and inflammatory cytokines (IL-1β and TNF-a) both in vitro and in an animal model of amyotrophic lateral sclerosis." (PMID 28790417, 2017). "When primary murine astrocytes were exposed to MCM collected from microglial models of Huntington’s disease (HD) and amyotrophic lateral sclerosis (ALS), they polarized to an A1-like phenotype and increased secretion of TNF-α and IL-1β." (PMID 36915214, 2023). "The elevated formation of inflammasomes, expression of IL-1β and IL-18, and excessive cleavage of GSDMD have been reported in amyotrophic lateral sclerosis (ALS) and multiple sclerosis (MS) cases, indicating a crucial role for pyroptosis in the neuroinflammation and development of ALS." (PMID 39337436, 2024). "Moreover, astroglia can express NLRP3 inflammasome and IL-1β under certain conditions, such as in SOD1 mouse model of amyotrophic lateral sclerosis (ALS) and human sporadic ALS patients, and amyloid β1–42-stimulated murine astrocytes." (PMID 32070376, 2020). "Furthermore, human mutations in (Cu/Zn) superoxide dismutase-1 (mSOD1) G93A and G85R, which cause non-cell-autonomous motor neuron death in amyotrophic lateral sclerosis (ALS), activate microglia and induce production of inflammatory mediators, including TNF-α, IL-1β, and NO." (PMID 23234315, 2012).
Arrhythmia (28 papers, 2010 to 2025). Any cardiac rhythm other than the normal sinus rhythm. "Another proinflammatory cytokine associated with arrhythmias is IL-1β, and its expression is also increased in chagasic mice as well as in patients with CCC." (PMID 40356773, 2025). "In line, inhibition of IL-1β in type 2 diabetes mellitus mice rescued the susceptibility to VA, implying that cytokine abundance contributes to arrhythmia burden in MI." (PMID 38099844, 2024). "In this context, TNF-α and IL-1β have been reported to boost susceptibility to arrhythmia in rat ventricular myocytes through increase of calcium leakage from the sarcoplasmic reticulum." (PMID 26977143, 2016). "Both left ventricular dysfunction and arrhythmias seem to be associated with IL‐1β increased levels in our patients, thus potentially confirming the role of this cytokine as a biomarker related to more severe cardiac mechanical and electrical abnormalities in LMNA patients." (PMID 34773379, 2021). "Thus, excessive IL-1β signaling and inflammation has been linked to increased incidence of arrhythmia and other AMI-related pathologies." (PMID 28659798, 2017). "IL-1β causes prolongation of the action potential duration, induces a decrease in potassium current and an increase in calcium sparks in cardiomyocytes, which are changes that underlie arrhythmia propensity." (PMID 27882934, 2016). "TNF-α and IL-1β arepotent pro-inflammatory cytokines that alter the electrical activity of atrialmyocytes, leading to arrhythmias." (PMID 40776948, 2025). "Other proinflammatory mediators that link neutrophils to arrhythmia in the context of MI include IL-1β, IL-6, and IL-17A." (PMID 38099844, 2024). "In line with our results, elevated levels of the inflammatory cytokines TNFα and IL-1β have been reported in both tissue and plasma from HF patients with arrhythmias." (PMID 29962957, 2018). "In cardiomyocytes, IL-1β then induces AP prolongation (through a decrease in Ito current) and an increase in Ca2+ sparks resulting in increased electrical vulnerability to arrhythmias." (PMID 27882934, 2016). "We further show that DM-induced arrhythmias can be successfully treated by inhibiting the IL-1β axis with either IL-1 receptor antagonist or by inhibiting the NLRP3 inflammasome." (PMID 27882934, 2016). "Studies from other group also revealed DM-induced arrhythmias could be successfully treated by inhibiting the IL-1β axis with either IL-1 receptor antagonist or by inhibiting the NLRP3 inflammasome." (PMID 33681353, 2021). "As we have shown that cardiac macrophages produce IL-1β and upregulate NLRP3 expression in response to TLR2 stimulation promoted by DM, we tested whether the NLRP3 inflammasome is involved in the DM-induced cardiac electrical disturbances and susceptibility to arrhythmias." (PMID 27882934, 2016). "Other authors using an experimental murine model of T. cruzi infection with Il-1r−/− and wild-type mice have suggested that IL-1β is not critical to the generation/maintenance of cardiac arrhythmias or systolic disfunction found in CCC patients." (PMID 39119291, 2024). "Since it is well accepted that KN-93 has numerous off target actions, including ionic currents with potential relevance to the observed arrhythmia phenotypes, a set of experiments were conducted using, the KN93 inactive analog KN92, either in the absence or presence of IL-1β." (PMID 27882934, 2016). "Also, in T1DM mice, released IL-1β from cardiac macrophages stimulated with TLR2 and NLRP3 agonists, induced a decrease in potassium current and an increase in calcium sparks in cardiomyocytes, and subsequent cardiac arrhythmia." (PMID 28659798, 2017). "“Normal” values are age and disease state-dependent, but for perspective, the case-matched controls with no arrhythmias in our atrial fibrillation study had mean DROMS 310 Carr units, Eh CySH −77 mV, Eh GSH −154 mV, IL-1β 0.4 pg/mL, IL-6 3.9 pg/mL, TNFα 5.5 pg/mL, and hsCRP 3.6 μg/mL." (PMID 20369058, 2010).
cystic fibrosis (28 papers, 2011 to 2025). Autosomal recessive disorder caused by pathogenic variants in the CFTR gene (cystic fibrosis transmembrane conductance regulator), which encodes a chloride and bicarbonate channel expressed in epithelial cells, and follow the diagnosis criteria. "Several reports have predicted the genetic association of IL1β with the development of Graves’ ophthalmopathy, ankylosing scleritis, and cystic fibrosis." (PMID 22128229, 2011). "A murine model based on mice carrying the most common CF mutation F508del CFTR (Cystic Fibrosis Transmembrane Conductance Regulator) also showed that excessive activation of IL-1β correlated with increased bacterial load, inflammation and lung damage." (PMID 32817626, 2020). "Neutralizing IL-1β antibodies reduced the bacterial burden and pulmonary inflammation induced by Pseudomonas aeruginosa in cystic fibrosis rodents and enhanced IL-1β activation upon exposure to Pseudomonas aeruginosa." (PMID 40136649, 2025). "The airway epithelial cells of individuals with cystic fibrosis were also triggered by IL-1β to release IL-8." (PMID 40136649, 2025). "Ensifentrine led to a robust reduction in the production of pro-inflammatory cytokines in cystic fibrosis bronchial epithelial cells treated with interleukin-1β (IL-1β)." (PMID 40978741, 2025). "A previous study has demonstrated that NLRC4 mediated IL-1R antagonist (IL-1Ra) through NF-κB to bind IL-1β, alleviating cystic fibrosis." (PMID 39052650, 2024). "The IL-1β produced further increases p62 levels resulting in defective autophagy in cystic fibrosis via accumulation of misfolded proteins in aggresomes." (PMID 32164793, 2020). "Under-acylated LPS from a P. aeruginosa cystic fibrosis isolate and from Rhodobacter sphaeroides elicited heterogeneous IL-1β responses in different human individuals." (PMID 29339744, 2018). "Overall, our findings help to explain the source of IL-1β secretion in cystic fibrosis patients with chronic airway infection due to P. aeruginosa where majority of the strains are T3SS-negative." (PMID 30062052, 2018). "Activation of the NLRC4 inflammasome is believed to contribute to high IL-1β production and pathogenicity in cystic fibrosis patients with chronic P. aeruginosa infection." (PMID 30062052, 2018). "The predominance of IL-1β mirrors what has been reported clinically using respiratory isolates of Pa isolated during the early stages of Pa infections from patients with cystic fibrosis, whereas the increase in IL-6 and TNF-α has parallels to what was seen in chronic Pa infections." (PMID 38792820, 2024). "Furthermore, cystic fibrosis patients have increased NE activity with elevated levels of pro-inflammatory cytokines IL-1β, IL-6, IL-8." (PMID 34869231, 2021). "In the IB3-1 cystic fibrosis cellular model, NF-κB-dependent genes, including the gene encoding for the proinflammatory protein IL-8, generally are activated following infection with P. aeruginosa or treatment with TNF-α or IL-1β." (PMID 29089668, 2017). "Studies demonstrated that the inhibition of TRPA1 results in a relevant reduction of the proinflammatory cytokines IL-1β and TNF-α in cystic fibrosis patients." (PMID 29682158, 2018). "In well differentiated human airway epithelial cells (HAE) from cystic fibrosis and non-CF patients, combined treatment with IL-1β and TNFα led to a decrease in transmembrane potential and tight junctional barrier function, the changes appearing more rapidly in CF cells." (PMID 21619599, 2011). "In pediatric cystic fibrosis patients, chemerin levels were comparable to healthy controls and did not correlate with nutritional status and levels of interleukin-1 beta (IL-1b), interleukin-6 (IL-6) and TNF α." (PMID 35327393, 2022). "Furthermore TRPA1 specific inhibitors from Hydra Biosciences (HC-030031) and Abbott (A-967079) inhibited P. aeruginosa induced transcription of IL8, IL1b, IL6 and tumor necrosis factor α (TNFα) in A549 and human cystic fibrosis cell line (CuFi-1)." (PMID 27827953, 2016).